EGFR (epidermal growth factor receptor)
Diseases named in the same sentence as EGFR in open-access papers (continued):
Sharing a sentence is not in itself a finding about the gene and the disease.
breast carcinoma (continued). "This study harnessed computational methodologies to assess the potential of nine thiazine-based derivatives as inhibitors of the epidermal growth factor receptor (EGFR) in breast cancer." (PMID 41552637, 2026). "For instance, PA-MSHA has been reported to suppress EGFR signaling in breast cancer cells and to induce an inflamed tumor phenotype that sensitizes tumors to antiPD-1 therapy." (PMID 41484455, 2026). "In this study, we explore the function of EGFR in breast cancer progression and the mechanistic basis of EGFR-targeted therapies, focusing on kinase inhibitors and protein degraders." (PMID 42190815, 2026). "In breast cancer, aberrant MAPK pathway activation is often caused by overexpression of upstream RTKs (e.g., EGFR, HER2) or mutations in oncogenes such as RAS and BRAF." (PMID 41510186, 2026). "This platform was created to treat breast cancer by combining EGFR inhibition with photodynamic therapy (PDT)." (PMID 41283276, 2025). "We previously reported that epidermal growth factor receptor (EGFR)+ ER+ breast cancer was associated with a poor patient prognosis compared to patients with EGFR- and ER+ breast cancer." (PMID 40422206, 2025). "In breast cancer cell lines, the EGFR expression was highest in MDA-MB-468, moderate in MDA-MB-231 and Hs578T, low expressed in MCF7, and minimal in MDA-MB-453." (PMID 40422194, 2025). "In contrast, although EGFR is highly expressed in breast cancer, EGFR inhibitors have shown limited clinical success in this context." (PMID 40806193, 2025). "Relatively small studies looking specifically at metaplastic breast carcinomas have observed amplification of EGFR in 33-37% of patients." (PMID 40501689, 2025). "The detailed mechanism of action of TSAC on EGFR/PI3K/AKt signaling in breast cancer requires further investigation." (PMID 40864816, 2025). "Further research into the mechanisms of EGFR in breast cancer is needed to better understand how to utilize EGFR–targeted therapies." (PMID 41026783, 2025). "EGFR was differentially expressed in response to ambrosin in bladder cancer and breast cancer cells." (PMID 40754248, 2025). "The dysregulation of EGFR signaling leads to uncontrolled cell proliferation and invasiveness in breast cancer." (PMID 40075637, 2025). "In this study, although EGFR is abundantly expressed on breast cancer cells, GE11 exhibited weaker tumor-targeting efficiency than cRGD, potentially due to its smaller molecular size and selective binding to a limited EGFR peptide region." (PMID 41216197, 2025). "Quantification of CEA, CA125, and EGFR on the surface of blood exosomes of six breast cancer patients and two healthy controls with a CD chip was able to identify breast cancer patients." (PMID 40075875, 2025). "These biomarkers are broadly categorized into predictive, such as specific receptors in breast cancer and EGFR in metastatic non-small cell lung cancer 35 and prognostic, which indicate disease progression, recurrence, or mortality." (PMID 39744576, 2025). "A meta-analysis involving more than 11,000 breast cancer patients revealed that elevated levels of RTKs, including HER2, EGFR and FGFR, are associated with increased breast cancer aggressiveness and decreased overall and disease-free survival." (PMID 40560045, 2025). "The epidermal growth factor receptor (EGFR) is a clinically important target, as its expression in patients with breast cancer influences both overall and disease-free survival." (PMID 41179692, 2025). "designed CD32A131R‐CAR T cells, which showed stronger killing activity against breast cancer cells overexpressing EGFR when used in combination with cetuximab and panitumumab." (PMID 40859900, 2025). "The group also showed that treating SKBR3 and HCC1954 breast cancer cells with lapatinib (inhibitor of EGFR/ErbB1 and ErbB2) led to a decrease in PHLDA1 as assessed by immunoblotting." (PMID 39630301, 2025).
breast carcinoma (continued). "The related, second-generation compound INCB7839 showed synergistic effects in inhibiting growth when combined with the dual EGFR/HER2 inhibitor GW2974 in MCF-7 breast cancer cells." (PMID 40427200, 2025). "The most potent compound was further investigated to understand its anticancer mechanisms, including its ability to induce apoptosis in NSCLC and breast cancer cells and its inhibition of EGFR." (PMID 40806193, 2025). "The findings revealed that microRNAs (miRNAs) modulated by EGFR in MSCs were potentially involved in cross-talk with breast cancer cells, highlighting the influence of the EGFR signaling system on MSCs." (PMID 41227364, 2025). "Other receptors that play a key role in breast cancer tumorigenesis are EGFR (epidermal growth factor receptor) and HER2." (PMID 40160874, 2025). "We treated T47D breast cancer cells with 100 nM E2 for 24 h under serum-free media conditions to identify the intermediary between ER and EGFR." (PMID 40422206, 2025). "LIPTACs exhibited efficient EGFR degradationon triple-negative breast cancer cell line HCC1143, the pancreatic cancer cell line PANC-1, as well as the nonsmall cell lungcancer cell line NCI-H1975." (PMID 41091621, 2025). "The study demonstrated that overexpression of HER2 led to increases in STAT1 and ACTA2 in EGFR+ breast cancer cells, whereas the use of the STAT1 inhibitor fludarabine resulted in decreased ACTA2 mRNA and HER2 protein levels." (PMID 40732340, 2025). "In total, 321 patients with breast cancer were included in the study, of whom 111 (34.6%) had EGFR+ status and the remaining 210 (65.4%) had EGFR- status." (PMID 41179692, 2025). "This, on one hand, explains the higher sensitivity of TNBC cells to CAP treatment than non-TNBC cells and, on the other hand, suggests the possibility of using EGFR in diagnosing the sensitivity of breast cancer patients to CAP treatment." (PMID 39781456, 2025). "In breast cancer, signaling axes such as EGFR, IGF, TGFβ, and HGF/c-Met critically regulate CSC expansion, particularly in aggressive subtypes like triple-negative tumors." (PMID 41373619, 2025). "Previous investigations have demonstrated that 1,25(OH)2D3 reduces EGFR mRNA and protein levels in breast cancer cells, and downregulates EGFR expression and signaling in A431 cells." (PMID 40872626, 2025). "Hyaluronan, a common ECM component, is known to facilitate EM resistance to EGFR/HER2 inhibitor lapatinib in breast cancers." (PMID 40313737, 2025). "In an in vivo model of breast cancer brain metastases (BCBMs), intratumoral administration of oncolytic herpes simplex virus (oHSV) and EGFR-CAR-NK-92 cells resulted in improved killing of cancer cells and longer survival, when compared to monotherapy." (PMID 40519903, 2025). "EGFR has been involved in many types of cancers, like breast cancer, head and neck squamous cell carcinoma, lung, pancreatic, and colorectal." (PMID 39802656, 2025). "Due to their potent activity against NSCLC and breast cancer, B-1 and B-2 were further examined for their potential to inhibit EGFR." (PMID 40806193, 2025). "EGFR is the most frequently altered driver gene in non-small-cell lung cancer (NSCLC), and its overexpression is also associated with breast cancer." (PMID 40806193, 2025). "Protein–protein interaction (STRING) analysis indicated that TGFB2 is associated with EGFR and MYC from the PAM50 breast cancer gene signature." (PMID 41373732, 2025). "Curcumin inhibits breast cancer’s progression, proliferation, and invasiveness by targeting the EGFR signaling pathway." (PMID 40563255, 2025). "In breast cancer, silencing the EGFR gene in the MDA-MB-468 cell line, which is highly resistant to drugs, increases the cells’ sensitivity to PHA-665752." (PMID 39859448, 2025). "The overexpression of the EGFR, gene amplification, and activating mutations are commonly observed in both NSCLC and certain subtypes of breast cancer." (PMID 40006082, 2025).
breast carcinoma (continued). "Analysis of the CCLE database revealed that EGFR expression in breast cancer tumor tissues is significantly higher than in other tissues." (PMID 40620253, 2025). "Upregulation of ANO1 has been shown to stimulate ERK1/2 signaling in breast cancer cells via CaMKII- and EGFR-mediated pathways." (PMID 40356890, 2025). "In this study, we developed an interpretable ML model based on ultrasound radiomic features to predict the EGFR expression status in breast cancer." (PMID 41179692, 2025). "EGFR overexpression is the result of 1) Amplification of the EGFR gene, observed in various cancers including breast cancer, non‐small‐cell lung cancer (NSCLC), and glioblastoma multiforme; 2) Overproduction at the transcriptional level." (PMID 40859900, 2025). "A similar effect was also observed in breast cancer for treatment with trastuzumab, monoclonal antibodies targeting EGFR." (PMID 39630301, 2025). "B-4 was shown to induce apoptosis in NSCLC and breast cancer cells and to significantly inhibit the EGFR." (PMID 40006082, 2025). "Meanwhile, TGFα-induced EGFR activation has been reported to promote tumor progression in cervical cancer, ovarian cancer, and breast cancer." (PMID 39885395, 2025). "Monocyte_1_IL1B exhibited a strong correlation with mechanistically related pathways, such as the ERBB2 − EGFR signaling pathway, which has been reported to promote the proliferation and migration of breast cancer cells." (PMID 41233852, 2025). "Beclin-1 mediates the cellular autophagy pathway, which is responsible for the degradation of the human epidermal growth factor 2 (HER2) in breast cancer and EGFR in NSCLC." (PMID 40243822, 2025). "Conversely, other studies have demonstrated the upregulation of EGFR and other human epidermal growth factor receptor family members in 3D breast cancer cells cultured in poly-HEMA- or Matrigel®- coated plates." (PMID 41228316, 2025). "Despite high levels of EGFR expression in breast cancer, EGFR TKIs have shown limited effectiveness, highlighting the need for the development of new small-molecule drug candidates." (PMID 40806193, 2025). "Pre-targeting MDA-MB-468 breast cancer cells with anti-PEG:anti-EGFR BsAbs significantly increased EGFP expression compared to pre-mixing (12- vs. 3-fold improvement over mRNA-LNPs alone)." (PMID 40235853, 2025). "Epidermal growth factor receptor (EGFR), also known as HER1, is overexpressed in at least 20% of breast cancers and is associated with poor prognosis in patients." (PMID 40705122, 2025). "For instance, EGFR inhibitors have shown limited efficacy in breast cancer patients, and frequent incidences of therapy resistance have been observed in head and neck cancer with EGFR-targeted inhibitors." (PMID 40560045, 2025). "The in vivo current study revealed a significant overexpression in EGFR gene expression in addition to an obvious reduction in ABCA1 gene expression upon DMBA induced breast cancer in rats." (PMID 39886047, 2025). "Basal-like bladder tumors overexpress epithelial lineage genes such as KRT5, KRT6A, KRT14, and epidermal growth factor receptor (EGFR), consistent with observations in basal breast cancer, SQCLC, and HNSCC." (PMID 40867349, 2025). "Previous studies have reported the downregulated EGFR in 3D cells in hormone-dependent breast cancer cells, but also in pancreatic ductal adenocarcinoma 3D cell cultures." (PMID 41228316, 2025). "The signaling pathway involving S1P is critical for epidermal growth factor receptor (EGFR) transactivation, which induces breast cancer migration, proliferation, and cell survival." (PMID 40002245, 2025).
breast carcinoma (continued). "The selection of EGFR and EpCAM as surface markers for isolating DTCs in our study represents a targeted approach, informed by their high prevalence in specific breast cancer subtypes." (PMID 40073025, 2025). "This study identified that EGFR amplification occurs in approximately 1-5% of breast cancer patients with shorter overall survival compared to unamplified patients." (PMID 40501689, 2025). "Molecular docking analysis showed that DAMNI had a promising binding affinity for ERα and EGFR, key receptors in breast cancer, with values of −5.8 and −4.7 kcal/mol, respectively." (PMID 40929235, 2025). "The strong anti-NSCLC and anti-breast cancer activity profile of B-4 led us to investigate its ability to inhibit the EGFR." (PMID 40006082, 2025). "Studies showed that E-cadherin contributes to a hyper-proliferative phenotype in breast cancer through its interaction with the transmembrane receptor EGFR." (PMID 40821783, 2025). "For example, oxidized resveratrol (ORes) significantly inhibited the proliferation and growth of breast cancer cells by inducing ferroptosis through inhibition of the EGFR/PI3K/AKT/GPX4 signaling axis." (PMID 40416989, 2025). "We present a reliable and interpretable tool for non-invasively assessing EGFR expression status in patients with breast cancer." (PMID 41179692, 2025). "Among various signaling pathways, the EGFR, ER, Notch, and Hedgehog signaling pathways have recently been identified as crucial in terms of breast cancer proliferation, survival, differentiation, maintenance of CSCs, and therapy failure." (PMID 39858015, 2025). "Depending on the study, EGFR gene amplification has been observed in 0.8-14% of breast cancer patients." (PMID 40501689, 2025). "To date, no studies have directly applied machine learning-based radiomics approaches on ultrasound imaging to predict EGFR expression status in breast cancer, highlighting a novel research gap addressed by this study." (PMID 41179692, 2025). "We now show that nEGFR can regulate NK cell recruitment and cytotoxicity in EGFR-dependent breast cancer." (PMID 39521886, 2025). "EGF Receptor (EGFR): ISGylation enhances EGFR recycling, sustaining Akt signaling and driving invasive breast cancer behavior." (PMID 40103488, 2025). "In this study, we developed and validated an interpretable ML model using ultrasound radiomic features to predict EGFR expression status in breast cancer." (PMID 41179692, 2025). "The most potent compound was further evaluated for its mechanistic anticancer effects, including inducing apoptosis in NSCLC and breast cancer cells and inhibiting the EGFR." (PMID 40006082, 2025). "EGFR (epidermal growth factor receptor) and EpCAM (epithelial cell adhesion molecule), two key cell surface markers in breast cancer, were validated as efficient cell capture targets for DTCs within microfluidic chambers." (PMID 40073025, 2025). "This pathway of EGFR activation has already been demonstrated in breast cancer, and HIF-1α reportedly induces HB-EGF shedding by ADAM12." (PMID 41346909, 2025). "Research has emphasized the potential of anti-EGFR targeted therapies, particularly when combined with monoclonal antibodies, to improve outcomes in the treatment of breast cancer." (PMID 40806193, 2025). "All fluorinated DDA bioisosteres exhibited improved cytotoxicity and more pronounced biological responses in EGFR+ breast cancer cells compared to tcyDTDO." (PMID 40867591, 2025). "TNF and VEGFA are more commonly seen in studies of drugs that promote and inhibit sex hormone secretion, and EGFR inhibits gonadal axis secretion in breast cancer patients." (PMID 40238841, 2025). "OC also plays a role in suppressing EMT and inhibiting the activation of important targets in breast cancer therapy such as EGFR, HER2, and c-MET." (PMID 40002421, 2025). "Lapatinib (Compound I) is an FDA-approved dual inhibitor of HER-2 and EGFR for HER2-positive breast cancer, granted approval in 2007." (PMID 41036428, 2025).
breast carcinoma (continued). "CDDO-Im downregulates the growth and metastasis of breast cancer by blocking the Epidermal growth factor receptor (EGFR)/Signal Transducer and Activator of Transcription 3 (STAT3)/Sox-2 pathways in Tumor-associated macrophages (TAMs)." (PMID 39926108, 2025). "The dysregulation of pathways, such as Wnt, FGF, SHH, Notch, EGFR, and BMP, can predispose individuals to breast cancer by promoting abnormal cell proliferation, survival, and tissue remodeling." (PMID 40075637, 2025). "SDC1 relies on the IL-6/STAT3, Notch and EGFR pathways to induce stem cell formation in breast cancer, Ibrahim et.al." (PMID 41364407, 2025). "The underlying mechanisms described so far are manifold and include activation of ERK via GADD45β in breast cancer or stimulation of the pathway at the receptor levels via HER1/EGFR." (PMID 40782795, 2025). "Further, the highest rate of amplification was in TNBC (3.2-6.7%), ER− (2.8-5.4%) and ER−/HER2+ tumors (1.3-6.5%), whereas EGFR amplification was relatively less common in ER+ breast cancers (0.8-1.4%)." (PMID 40501689, 2025). "While neratinib is approved for the treatment of HER2-positive breast cancer, it also has activity against the epidermal growth factor receptor (EGFR) tyrosine kinase." (PMID 40777112, 2025). "In breast cancer cells, nuclear EGFR inhibits NK cell recruitment and cytotoxicity, while treatment with cSNX1.3 significantly improves NK cell recruitment and cytotoxicity, although this newly discovered mechanism requires further in‐depth exploration." (PMID 40859900, 2025). "GPRC5A also exhibits a tumour-suppressive effect in breast cancer cells by inhibiting EGFR (epidermal growth factor receptor)." (PMID 40427604, 2025). "The current results highlighted the significance of evaluating DAMNI as a prospective ERα and EGFR inhibitor in experimental assays in order to overcome breast cancer disease." (PMID 40929235, 2025). "EGFR (HER1) and ERBB2 (HER2) are frequently implicated in breast, lung, ovarian, and other malignancies, whereas ERBB3 (HER3) is commonly associated with breast cancer, and ERBB4 (HER4) has been detected in both breast cancer and granulosa cell tumors." (PMID 41230212, 2025). "Particularly, cross-talk between the calcium-sensing receptor and the EGFR in MCF-7 breast cancer cell proliferation has been observed, and cooperative signaling between calcium and EGF on tumor cells has also been observed." (PMID 39940827, 2025). "We tested NKCE killing specificity on HeLa cells, a breast cancer cell line expressing both EGFR and B7-H6, or SK-BR-3 cells, a breast cancer cell line expressing both HER2 and B7-H6." (PMID 39811682, 2025). "We show that NK cells are preferentially recruited to tumors and cells treated with cSNX1.3 and that cSNX1.3 treatment also results in enhanced NK cell killing of EGFR-expressing breast cancer cells." (PMID 39521886, 2025). "Molecular docking and molecular dynamics simulations were employed to evaluate the interactions between camptothecin and two receptors overexpressed in breast cancer: EGFR and HER2." (PMID 40136447, 2025). "ERα and EGFR appear to be promising receptors for designing inhibitors used in targeted therapies developed for breast cancer." (PMID 40929235, 2025). "GE11, a 12-amino-acid peptide, binds to the epidermal growth factor receptor (EGFR), which is overexpressed in 40–70% of breast cancers, particularly TNBC and HER2-positive subtypes." (PMID 41216197, 2025). "We conclude that EGFR amplification with co-incident PI3K pathway mutations are driver mutations in a subset of breast cancers and present a subgroup of breast cancers that are more likely to respond to dual targeted therapy." (PMID 40501689, 2025). "Inhibition of FAK has shown synergistic apoptotic effects with EGF receptor blockade in breast cancer, suggesting that disrupting phospholipid synthesis via FASN inhibition impairs EGFR localization, attenuates FAK-associated signaling, and induces apoptosis." (PMID 40733158, 2025).